MIR376A2 (microRNA 376a-2)
Synonyms: hsa-mir-376a-2; MIR376A-2; MIRN376A-2; MIRN376A2; mir-376a-2
Gene: MicroRNA gene on chromosome 14 (101,040,069 to 101,040,148, forward strand). Ensembl gene ENSG00000283561.
Gene Ontology:
Biological process: miRNA-mediated post-transcriptional gene silencing
Cellular component: RISC complex